MIR7106 (microRNA 7106)
Synonyms: hsa-mir-7106
Gene: MicroRNA gene on chromosome 12 (113,159,113 to 113,159,177, reverse strand). Ensembl gene ENSG00000276908.
Homologues: Orthologues: chimpanzee MIR7106 (100% identical).